ERAP2 (endoplasmic reticulum aminopeptidase 2)
Description:
Aminopeptidase that plays a central role in peptide trimming, a step required for the generation of most HLA class I-binding peptides. Peptide trimming is essential to customize longer precursor peptides to fit them to the correct length required for presentation on MHC class I molecules. Preferentially hydrolyzes the basic residues Arg and Lys.
Synonyms: L-RAP; LRAP
Tractability: Small molecule: a drug acting on it is in phase 2 or 3 trials; a structure with a bound ligand is known; a high-quality ligand is known. Antibody: UniProt predicts a signal peptide or a membrane-spanning region. PROTAC: ubiquitination databases record sites on it; its protein half-life has been measured; a small molecule that binds it is known.
Target class: Protease; Enzyme; Metallo protease; Metallo protease MAE clan; Metallo protease M1 family
Gene: Protein-coding gene on chromosome 5 (96,875,986 to 96,919,703, forward strand). Ensembl gene ENSG00000164308.
Subcellular location: Endoplasmic reticulum membrane
Subcellular location (Human Protein Atlas): Golgi apparatus; Predicted to be secreted
Pathways (Reactome):
Immune System: Antigen Presentation: Folding, assembly and peptide loading of class I MHC
Gene Ontology:
Molecular function: aminopeptidase activity; endopeptidase activity; metallopeptidase activity; protein binding; metalloaminopeptidase activity; zinc ion binding
Biological process: antigen processing and presentation of peptide antigen via MHC class I; antigen processing and presentation of endogenous peptide antigen via MHC class I; peptide catabolic process; proteolysis; regulation of blood pressure
Cellular component: endoplasmic reticulum; endoplasmic reticulum lumen; peptidase complex; cytoplasm; endoplasmic reticulum membrane
Genetic constraint (gnomAD): Loss-of-function variants: 101 observed, 92.8 expected, observed/expected ratio (o/e) 1.09, 90% interval 0.93 to 1.28. The upper end of that interval is the gene's LOEUF score, 1.28, which puts it in group 5 of 6, group 1 being the genes least tolerant of losing a copy. Missense variants: 999 observed, 1,012.6 expected, observed/expected ratio (o/e) 0.99, 90% interval 0.94 to 1.04. Synonymous variants: 362 observed, 367.5 expected, observed/expected ratio (o/e) 0.99, 90% interval 0.9 to 1.08.
Homologues: Orthologues: chimpanzee ERAP2 (99% identical), macaque ERAP2 (94% identical), pig ERAP2 (82% identical), zebrafish erap2 (56% identical), Drosophila melanogaster SP1029 (30% identical), Drosophila melanogaster CG46339 (29% identical), Drosophila melanogaster CG31445 (29% identical), Caenorhabditis elegans F49B2.6 (27% identical), Caenorhabditis elegans anp-1 (27% identical), Drosophila melanogaster CG31233 (26% identical), Drosophila melanogaster CG3502 (26% identical), Drosophila melanogaster CG2111 (25% identical), and 6 more. Paralogues in human: ERAP1 (49% identical), LNPEP (42% identical), ENPEP (32% identical), ANPEP (31% identical), NPEPPS (31% identical), LVRN (29% identical), TRHDE (25% identical), RNPEP (12% identical), RNPEPL1 (11% identical), LTA4H (11% identical), AOPEP (11% identical).
Diseases named in the same sentence as ERAP2 in open-access papers:
ERAP2 is named in the same sentence as 89 diseases in open-access papers, as found by Europe PMC text mining. Sharing a sentence is not in itself a finding about the gene and the disease. The quoted sentences say what the papers report.
preeclampsia (20 papers, 2011 to 2025). Preeclampsia is a hypertensive disorder of pregnancy that is characterized by new-onset hypertension with proteinuria presenting after 20 weeks of gestation, and depending on mild or severe forms may initially present with severe headache, visual disturbances, and hyperreflexia. "The association between the risk of preeclampsia and the maternal ERAP2 rs2549782 and rs17408150 polymorphisms was assessed through a meta-analysis of three studies." (PMID 39194706, 2024). "The polymorphism of the ERAP2 gene was associated with several immune-mediated diseases including AS, psoriasis and preeclampsia." (PMID 39906739, 2024). "ERAP2, expressed in the placenta, has been linked to the onset and progression of preeclampsia, while RAC1 is involved in regulating placental growth." (PMID 39687015, 2024). "As result, ERAP2 haplotype rs2549796–rs2927609–rs11135484 was associated with preeclampsia (corrected p = 0.0109)." (PMID 33762660, 2021). "The present study confirmed a genetic association between ERAP2 and preeclampsia, and, for the first time, reported an association between ERAP1 and eclampsia." (PMID 33762660, 2021). "In conclusion, ERAP1 gene is associated with eclampsia whereas ERAP2 is associated with preeclampsia, although the mechanism by which genetic variants in ERAPs influence the risk of preeclampsia and eclampsia remain to be elucidated." (PMID 33762660, 2021). "In conclusion, we identified genetic variants in ERAP1 and ERAP2 associated with eclampsia and preeclampsia, respectively." (PMID 33762660, 2021). "The role of LNPEP in the RAS is well-documented as well as the association of ERAP2 with preeclampsia." (PMID 32793222, 2020). "This is also suggested by the association of ERAP2 with a wider array of diseases, such as preeclampsia or IBD." (PMID 32793222, 2020). "This study attempted to disclose the possible implications of the ERAP1 and ERAP2 gene polymorphisms in predisposing the pregnant women to preeclampsia using Real-Time allelic discrimination Taq-Man assays." (PMID 31223582, 2019). "Ongoing investigation resulted differently from before performed studies considering the role of ERAP1 and ERAP2 gene polymorphisms in predisposing women to preeclampsia, emphasizing on the genetic structure differences among various racial populations." (PMID 31223582, 2019). "(iii) Small case–control studies provided evidence that polymorphic variants of ERAP1 and ERAP2 are associated with preeclampsia and hypertension." (PMID 29850473, 2018). "Single nucleotide polymorphisms (SNPs) in the endoplasmic reticulum aminopeptidase 2 (ERAP2) gene are associated with preeclampsia (PE) in different populations." (PMID 24040622, 2013). "More recently, variants of ERAP1 and ERAP2 have been found to be associated with an increased risk of preeclampsia, a heritable pregnancy specific disorder characterized by new-onset hypertension and proteinuria." (PMID 22942706, 2012). "In the case of ACVR2A and ERAP2 we subsequently were able to demonstrate association with preeclampsia in the Norwegian population using other SNPs in these genes, providing evidence of different allele frequencies and LD patterns at these loci." (PMID 22432041, 2012). "Although ERAP2 was associated with risk for preeclampsia in both populations, different polymorphisms of the gene were identified in each group." (PMID 21569342, 2011). "A second potential source of variation between ethnicities is the finding that two different SNPs in the ERAP2 gene are associated with risk for preeclampsia." (PMID 21569342, 2011). "In conjunction with previous studies, which have found maternal associations with this gene in an Australian/New Zealand population and a Norwegian population, ERAP2 has now been associated with preeclampsia in three populations." (PMID 21569342, 2011).
preeclampsia (continued). "ERAP2 appears to contribute to the risk for preeclampsia in three of the ethnic groups, with two different allelic variants being associated with risk." (PMID 21569342, 2011). "In contrast to the previous study, we also included fetal samples to determine if the fetal ERAP2 gene was associated with risk for preeclampsia." (PMID 21569342, 2011). "We found that, in African Americans, the presence of the minor allele (G) of the rs2549782 SNP in the fetal ERAP2 gene increased the risk for preeclampsia." (PMID 21569342, 2011). "The association of rs2549782 with risk for preeclampsia is consistent with findings of a previous study that found an association of maternal ERAP2 alleles in an Australian/New Zealand population." (PMID 21569342, 2011). "We examined the association between ERAP2 and risk for preeclampsia in two distinct case-control cohorts: Chilean (1103 maternal-fetal dyads) and African American (836 maternal and 837 fetal samples)." (PMID 21569342, 2011). "There is also the potential for both the maternal and fetal ERAP2 genes to contribute to the risk for preeclampsia in a single ethnic population." (PMID 21569342, 2011). "A case-control design was used to test for associations between two SNPs in ERAP2, rs2549782 and rs17408150, and preeclampsia status in 1103 Chilean maternal-fetal dyads and 1637 unpaired African American samples (836 maternal, 837 fetal)." (PMID 21569342, 2011). "Two different single nucleotide polymorphisms (SNPs) in the endoplasmic reticulum aminopeptidase 2 (ERAP2) gene were recently reported to be associated with increased risk for preeclampsia in two different populations." (PMID 21569342, 2011). "Our results show that fetal carriage of the minor allele (G) of rs2549782 in the ERAP2 gene increases the risk for preeclampsia in African Americans." (PMID 21569342, 2011). "Although a number of missense single nucleotide polymorphisms (SNP) in ERAP2 have been associated with an increased risk of preeclampsia, the functional importance of these SNPs is still not fully understood." (PMID 21999197, 2011). "The endoplasmic reticulum aminopeptidase 2 (ERAP2) gene is associated with preeclampsia (PE)." (PMID 34445292, 2021). "Interestingly, the fetal minor allele for variant rs2549782 (ERAP2) was associated with preeclampsia in African American population." (PMID 33762660, 2021). "The genotype C/C, in ERAP1 rs30187 variant (c.1583 T > C, p.Lys528Arg), was associated with increased risk of eclampsia (OR = 1.85, p = 0.019) whereas ERAP2 haplotype rs2549796(C)–rs2927609(C)–rs11135484(G) was associated with preeclampsia (OR = 1.96, corrected p-value = 0.01)." (PMID 33762660, 2021). "Furthermore, genetic–molecular approaches have identified variants among ERAP1 and ERAP2 genes that are associated with preeclampsia, hemolytic uremia, and hypertension." (PMID 29850473, 2018). "The identification of ERAP2 as a gene that was significantly down-regulated in dystocia is of particular interest because ERAP2 has been identified as a genetic susceptibility locus for preeclampsia in a number of different populations." (PMID 21999197, 2011). "We report an association between fetal ERAP2 and preeclampsia in an African American population." (PMID 21569342, 2011). "In the present study, we sought to test whether there were associations between the two previously identified SNPs in ERAP2 and risk for preeclampsia in two distinct ethnic sample sets, Chilean and African American." (PMID 21569342, 2011). "Indeed ERAP2, besides its function as peptide trimmer, has also been found to play a role in the AngII conversion in AngIII and AngIV and consequently, in the predisposition to preeclampsia via the RAS." (PMID 32793222, 2020). "Two other proteins associated with the development of preeclampsia and affected by CHEM in this study are Tubulointerstitial nephritis antigen-like 1 (TINAGL1) and Endoplasmic Reticulum Aminopeptidase 2 (ERAP2)." (PMID 35406725, 2022).
preeclampsia (continued). "Seven alleles were significantly or marginally significantly associated with preeclampsia, which involved six genes (rs4762 in AGT, rs1800896 in IL-10, rs1800629 and rs1799724 in TNFα, rs2070744 in NOS3, rs7412 in APOE, and rs2549782 in ERAP2)." (PMID 30112393, 2018). "Of note, ERAP2 expression was previously found altered in first trimester placentas of women prone to develop preeclampsia." (PMID 22942706, 2012). "Defects in the RAS system have been demonstrated both in the maternal system and fetal tissue, further emphasizing the potential for ERAP2 to be involved in the pathophysiology of preeclampsia." (PMID 21569342, 2011). "ERAP2 has the potential to contribute to the development of preeclampsia in multiple ways due to its involvement in the regulation of immune responses, pro-inflammatory cytokine production, and blood pressure." (PMID 21569342, 2011). "It was recently shown that ERAP2 expression was altered in first trimester placentas of pregnancies destined to develop preeclampsia." (PMID 21569342, 2011). "ERAP2 is expressed in placental tissue and it is involved in immune responses, inflammation, and blood pressure regulation; making it is an attractive preeclampsia candidate gene." (PMID 21569342, 2011). "A study conducted to investigate the lack of association of the rs2549782 SNP with preeclampsia in Chileans showed that, unlike other populations, there is a lack of LD between rs2549782 and rs2248374 SNPs, reflecting different ERAP2 haplotypes." (PMID 38980912, 2024). "Moreover, studies reported that ERAP2 abundance is lower in the placenta of women with preeclampsia." (PMID 35406725, 2022). "Predicted deleterious variants in ROCK2, AVCR2A, ERAP1, and ERAP2 in women with (cases) and without (controls) preeclampsia." (PMID 29758065, 2018). "This provides strong evidence that ERAP2 plays a role in the development of preeclampsia." (PMID 21569342, 2011). "Our findings did not support a genetic association between ERAP2 and the risk for preeclampsia in either the Chilean population or the maternal African American population." (PMID 21569342, 2011). "Furthermore, ERAP2 expression is altered in first trimester placentas of women destined to develop preeclampsia." (PMID 21569342, 2011). "ERAP2 is expressed in the syncytiotrophoblast and it has been reported that expression of this gene was down-regulated in first trimester placentas of women who subsequently developed preeclampsia." (PMID 21569342, 2011). "Large-scale family studies have identified associations between preeclampsia and genetic variations in ACVR2 (activin A receptor type 2A), ROCK2 (coiled-coil-containing protein kinase 2), ERAP1 (endoplasmic reticulum aminopeptidase 1), and ERAP2 (endoplasmic reticulum aminopeptidase 2)." (PMID 40507612, 2025). "However, increased ERAP2 expression is in general associated with risk of chronic inflammatory diseases, including IBD (especially Crohn’s disease), ankylosing spondylitis, birdshot chorioretinopathy, psoriasis, preeclampsia, and hypertension." (PMID 39123229, 2024). "Furthermore, we only tested for associations between two SNPs in the ERAP2 gene so we are unable to rule out the possibility that different variants of this gene are associated with risk for preeclampsia in these populations." (PMID 21569342, 2011). "Thus, the question still remains whether both maternal and fetal ERAP2 contribute to preeclampsia in different ethnic populations where only maternal genes were tested." (PMID 21569342, 2011). "Finally, we investigated the presence of variants in four selected genes previously reported in relation to preeclampsia; the ROCK2, ACVR2A, ERAP1, and ERAP2 genes." (PMID 29758065, 2018). "ERAP2 Allelic analysis for maternal and fetal samples with and without preeclampsia." (PMID 21569342, 2011).
preeclampsia (continued). "Even though the comprehensive understanding of ERAP2 lags that of ERAP1 due to the lack of an animal model, recent studies have shown that both enzymes are associated with an increased risk of several diseases, including pregnancy disorder pre-eclampsia (PE), recurrent miscarriages, and cancer." (PMID 36834865, 2023).
autoimmune disease (18 papers, 2020 to 2025). A disorder resulting from loss of function or tissue destruction of an organ or multiple organs, arising from humoral or cellular immune responses of the individual to their own tissue constituents. "ERAP2 is known to be an aminopeptidase involved in the pathophysiology of autoimmune diseases, and the ERAP2/ERAP1 ratio results has been linked to increased autoimmunity risk." (PMID 40574847, 2025). "ERAP2 is reported to be associated with several other autoimmune diseases and is, as the TAP1 and TAP2 proteins, crucial for proper folding and assembly of the MHC-I heavy chain." (PMID 40883722, 2025). "Variation in ERAP1 and ERAP2 genes underwent selection during the Black Death and impact autoimmune disease susceptibility." (PMID 41428259, 2025). "ERAP2 gene polymorphisms, linked to resistance against lethal infections and susceptibility to autoimmune diseases including IBD, affect T-cell immune responses by processing antigen peptides." (PMID 39144148, 2024). "Additional SNVs control ERAP2 expression by mechanisms other than alternative splicing, and variants linked to autoimmune diseases also alter enhancer-promoter interactions of ERAP2 leading to increased expression levels." (PMID 37925533, 2023). "The ERAP2 gene is highly polymorphic and encodes haplotypes that confer resistance against lethal infectious diseases, but also increase the risk for autoimmune disorders." (PMID 37925533, 2023). "IFI30 has been implicated in the pathogenesis of some autoimmune diseases, and genetic polymorphisms of ERAP2 and its paralog ERAP1 are associated with increased susceptibility to autoimmune/chronic inflammatory disorders." (PMID 35954309, 2022). "Genetic variants of ERAP1 and ERAP2 genes can increase the susceptibility to autoimmune diseases, cancer and infectious diseases." (PMID 33679890, 2021). "ERAP2 increases susceptibility to autoimmune diseases, infectious diseases, and cancer because of its genetic variability." (PMID 32596278, 2020). "ERAP2 is closely associated with autoimmune diseases and cell pyroptosis." (PMID 38273310, 2024). "Due to its genetic association with several autoimmune diseases, ERAP2 may promote T-cell recognition of autoantigens, which contributes to destructive inflammation." (PMID 37925533, 2023). "Susceptibility to autoimmune diseases in the human population may be related to ERAP2 haplotypes that show evidence for natural selection in recent history because they are associated with resistance to infection as revealed by ancient genome studies." (PMID 37925533, 2023). "Abnormal expansion of the VNTR might increase autoimmune disease risk through reducing ERAP2 expression, leaving longer and more antigenic peptides, yet potentially higher fitness against virus infection." (PMID 34253730, 2021). "Mann–Whitney U tests were conducted to compare GenePy scores for ERAP1 and ERAP2 between those with isolated CD and CD and ≥ 1 autoimmune disease diagnosis and those with isolated UC and UC and ≥ 1 autoimmune disease diagnosis." (PMID 41428259, 2025). "ERAP1 and ERAP2 play crucial roles in the modulation of the immune response, making them attractive targets for therapeutic intervention, especially in autoimmune diseases." (PMID 40226591, 2025). "The ERAP1/ERAP2/LNPEP aminopeptidases are involved in antigen processing and variation is linked to multiple autoimmune diseases." (PMID 38421405, 2024). "ERAP2 is a key enzyme in the generation of antigenic epitopes on the cell surface which trigger immune responses, making them potential targets for autoimmune diseases." (PMID 38273310, 2024). "ERAP2 regulates the immunopeptidome on the cell surface which triggers immune responses via T cells and is thus a potential target for treating autoimmune diseases, cancer, or viral infections." (PMID 38273310, 2024). "ERAP2 was also involved in autoimmune diseases, such as ankylosing spondylitis, whose etiology is unclear." (PMID 34992605, 2021).
autoimmune disease (continued). "Indeed, increased ERAP1 and ERAP2 expression was demonstrated to raise the odds of developing a number of autoimmune diseases such as Chron, Beçhet’s disease, Birdshot Chorioretinopathy and Type I diabetes." (PMID 39839670, 2024). "On the other hand, the lack of ERAP2 may, in many instances, prevent it from overtrimming antigenic peptides produced by ERAP1, which are necessary to fight infection or contribute to autoimmune disease." (PMID 35769458, 2022).